HLX (H2.0 like homeobox)
Description:
Transcription factor required for TBX21/T-bet-dependent maturation of Th1 cells as well as maintenance of Th1-specific gene expression. Involved in embryogenesis and hematopoiesis (By similarity).
Synonyms: HLX1; HB24
Tractability: PROTAC: ubiquitination databases record sites on it.
Gene: Protein-coding gene on chromosome 1 (220,879,431 to 220,885,059, forward strand). Ensembl gene ENSG00000136630.
Subcellular location: Nucleus
Subcellular location (Human Protein Atlas): Cytosol; Nucleoplasm
Gene Ontology:
Molecular function: protein binding; sequence-specific DNA binding; DNA-binding transcription factor activity, RNA polymerase II-specific; DNA binding
Biological process: signal transduction; regulation of DNA-templated transcription; regulation of transcription by RNA polymerase II
Cellular component: chromatin; nucleus
Genetic constraint (gnomAD): Loss-of-function variants: 6 observed, 28.52 expected, observed/expected ratio (o/e) 0.21, 90% interval 0.11 to 0.41. The upper end of that interval is the gene's LOEUF score, 0.41, which puts it in group 1 of 6, group 1 being the genes least tolerant of losing a copy. Missense variants: 666 observed, 656.66 expected, observed/expected ratio (o/e) 1.01, 90% interval 0.95 to 1.08. Synonymous variants: 328 observed, 296.61 expected, observed/expected ratio (o/e) 1.11, 90% interval 1.01 to 1.21.
Homologues: Orthologues: chimpanzee HLX (99% identical), macaque HLX (97% identical), rabbit HLX (89% identical), rat Hlx (87% identical), pig HLX (87% identical), mouse Hlx (86% identical), dog HLX (85% identical), guinea pig HLX (66% identical), tropical clawed frog hlx (46% identical), zebrafish hlx1 (43% identical), Drosophila melanogaster H2.0 (25% identical). Paralogues in human: DBX1 (22% identical), DBX2 (19% identical), LEUTX (7% identical).